CD24 (CD24 molecule)
Diseases named in the same sentence as CD24 in open-access papers (continued):
Sharing a sentence is not in itself a finding about the gene and the disease.
gastric cancer (continued). "Taken together, these findings demonstrate that RhoA function is necessary for CD24-mediated EGFR stability in gastric cancer SGC-7901 cells." (PMID 26830684, 2016). "Among 41 gastric cancer cases, we found that both CD24 and EGFR expression level was markedly increased in low-differentiated tumor tissues when compared with their matched highly-differentiated tumor tissues." (PMID 26830684, 2016). "In this report, SGC-7901 gastric cancer cells depleting CD24 showed significant reductions in phosphorylation of ERK and Akt proteins as well as increases in E-cadherin expression levels." (PMID 26830684, 2016). "Collectively, these data suggest that CD24 modulates EGFR subcellular location in gastric cancer cells." (PMID 26830684, 2016). "In the present study, the fact that depletion of CD24 leading to low expression of EGFR in gastric cancer cells attracted our attention." (PMID 26830684, 2016). "Because the gastric cancer tissue samples we studied here were from China, we used the two gastric cancer cell lines derived from Chinese gastric carcinoma patients to study the regulation of EGFR by CD24." (PMID 26830684, 2016). "Aberrant activation CD24 signaling contributes to malignant progression of gastric cancer has been demonstrated recently." (PMID 26830684, 2016). "Although CD24 was detected on the cytoplasm in gastric cancer cells as other report suggested, we were surprised to observe that CD24 was localized to the cell membrane, where it was partially co-localized and interacted with EGFR." (PMID 26830684, 2016). "Taken together, these observations suggest that CD24 knockdown impairs EGFR function in gastric cancer cells." (PMID 26830684, 2016). "In the present study, we investigated the relevance of EGFR expression in CD24 positive gastric cancer." (PMID 26830684, 2016). "Ectopic expression of CD24 in gastric epithelial cells augmented the expression of EGFR, while knockdown of CD24 in gastric cancer cells decreased the level of EGFR and cell migration velocity." (PMID 26830684, 2016). "Positive immunohistochemical staining for cytoplasmic CD24 was related to more advance staging in patients with gastric cancer." (PMID 26394139, 2015). "This study aimed to explore changes in CD44 and CD24 expression levels in patients with gastric cancer and to assess their prognostic values." (PMID 25212506, 2014). "The pooled hazard ratio (HR) for OS showed overexpression of CD24 reduced OS in gastric cancer (HR = 1.99, 95% CI = 1.29–3.07, P = 0.002)." (PMID 25503963, 2014). "Previous investigation of the correlation between CD24/CD44 expression and gastric cancer revealed that CD24(+) patients had a higher likelihood of gastric cancer recurrence than CD24(−) patients." (PMID 25212506, 2014). "The prognostic significance of CD24 expression for survival in patients with gastric cancer remains controversial." (PMID 25503963, 2014). "We conducted a meta-analysis to investigate the impact of CD24 expression on clinicopathological features and survival outcomes in gastric cancer." (PMID 25503963, 2014). "The purpose of this study was to evaluate the correlation of CD44/CD24 expression with recurrent gastric cancer and to determine its prognostic significance." (PMID 22839505, 2012). "The role of CD44 and CD24 expression in gastric carcinoma has been explored for nearly thirty years." (PMID 22839505, 2012). "CD24 is a cell-surface glycosylated protein and one of the markers for gastric cancer stem cells." (PMID 39895782, 2025). "There is a correlation between invasiveness, metastasis, and CD24 expression in gastric cancer." (PMID 37529165, 2023). "IL-10-expressing CD24+CD38+ Bregs were characterized in gastric cancer (GC) patients." (PMID 33193391, 2020). "In addition, we noticed that the effect of CD24 on EGFR stability was mediated by RhoA activity in SGC-7901 gastric cancer cells." (PMID 26830684, 2016).
gastric cancer (continued). "Overall, the clinical data support our in vitro results that CD24 may play a role as an EGFR supporter to promote gastric cancer progression." (PMID 26830684, 2016). "To investigate whether our experimental findings could be relevant to the pathogenesis of gastric cancer in humans, we examined CD24 and EGFR expression patterns in high and low degree differentiated gastric cancers." (PMID 26830684, 2016). "Interestingly, in SGC-7901 gastric cancer cells, CD24 was shown to maintain the expression of EGFR through a RhoA-dependent manner." (PMID 26830684, 2016). "Moreover, analysis of gastric cancer specimens also showed a positive correlation between CD24 and EGFR expression." (PMID 26830684, 2016). "Although CD24 exerts its biological impacts based on multiple mechanisms, how CD24 contributes to gastric cancer progression remains largely unknown." (PMID 26830684, 2016). "Overall, the fact that CD24 interacted with EGFR and was crucial for activation of EGFR downstream effectors and cell migration, allowing us to conclude that regulation of EGFR stabilized expression can thus be a novel mechanism for CD24-induced gastric cancer progression." (PMID 26830684, 2016). "After adjusting for other risk factors, the association of CD44/CD24 expression with gastric cancer recurrence was still not significant." (PMID 22839505, 2012). "Therefore, we decided to investigate the expression of adhesion molecule CD44/CD24 in recurrent gastric cancer and its possible predictive relevance in future clinical practice." (PMID 22839505, 2012). "No significance was shown in the crude association of CD44/CD24 expression with gastric cancer recurrence." (PMID 22839505, 2012). "Based on the implications of these previous studies, we hypothesized that CD44+/CD24- expression might be correlated with gastric cancer recurrence." (PMID 22839505, 2012). "Neither individual expression of CD24 or CD44, nor combined expression of CD44/CD24 was associated with recurrence of gastric carcinoma." (PMID 22839505, 2012). "Previously, we described an extended phenotype of gastric cancer stem cells (GCSCs; CD24+CD44+CD54+EpCAM+) that is associated with metastasis and tumor stage in GC patients." (PMID 39148939, 2024). "However, same characteristics are represented by CD44+ CD24+ cells in gastric cancer." (PMID 37529165, 2023). "In addition, CD24 overexpression could indicate tumor invasiveness and a prognosis marker in gastric cancer (GC)." (PMID 31614769, 2019). "Overexpression of ACAT1 in gastric cancer cells resulted in decreased expression levels of CD44 and OCT4, while the expression level of CD24 increased." (PMID 39247186, 2024). "Contrary to the positive regulatory role of HIF-1α on CD44 and CD24, HIF-1α exhibited a negative regulatory effect on CD133 in a panel of gastric cancer cell lines." (PMID 36846589, 2023). "The MKN45 cells with GRP78 knockdown exhibited decreased formation of colonies and spheroids and decreased expression of gastric cancer stem cell–like markers (LGR5, CD24, CD44, and ALDH1) and stemness-related transcriptional factors (SOX2 and Nanog)." (PMID 35740372, 2022). "Knockdown of GRP78 expression or inhibition of GRP78 by ISL downregulated CD24, CD44, LGR5, SOX2, and Nanog in gastric cancer in our study." (PMID 35740372, 2022). "In the present work and a previous study, we successfully isolated GCSC spheres from gastric cancer cell lines, MKN28 and SGC-7901, and found that GCSCs express high levels of stem cell surface markers, including CD24, CD44, and OCT4." (PMID 29422082, 2018). "Both CD24 and LGR5 are gastric cancer stem cell biomarkers expressed simultaneously in gastric cancer tissues, whereas Ki67 is involved in the formation of gastric adenocarcinoma." (PMID 28968998, 2017).
gastric cancer (continued). "Another phenomenon we noticed here was that, in serum-starved conditions, CD24-knockdown cells had lower EGFR expression compared to control cells, and such difference was apparent before and after the gastric cancer cells were stimulated with EGF." (PMID 26830684, 2016). "To assess the effect of CD24 on total EGFR level, we transfected human gastric cancer cells SGC-7901 with control siRNA or siRNA for CD24." (PMID 26830684, 2016). "Together, our results indicate that CD24 plays an important role in regulating EGFR and EGFR-initiated signaling in gastric cancer." (PMID 26830684, 2016). "Since the knockdown of CD24 by siRNA inhibited EGFR expression, we further analyzed the effect of CD24 on EGFR related signaling pathway in gastric cancer cells." (PMID 26830684, 2016). "CD24 and CD44 expression levels were significantly higher in patients with gastric cancer compared with those in paired controls (45.5% vs. 0.0%, and 61.0% vs. 0.0%, P < 0.001)." (PMID 25212506, 2014). "The aim of this study was therefore to evaluate the expression levels of CD24 and CD44 in gastric cancer and to evaluate their possible predictive relevance for future clinical practice." (PMID 25212506, 2014). "The mRNA expression levels of CD24 and CD44 were consistent with the immunohistochemistry results in gastric cancer." (PMID 25212506, 2014). "Among 77 paired samples, CD24(+) and CD44(+) staining results were found in 35/77 (45.5%) and 47/77 (61.0%) of the gastric cancer samples, respectively." (PMID 25212506, 2014). "Similarly, we observed a significant increase in CIC markers, such as CD44, CD44v9, and CD24, in ECF-R gastric cancer cells compared with those in the parental cells." (PMID 40518514, 2025). "In gastric cancer stem cells, CD44 is overexpressed while CD24 is under expressed." (PMID 39247186, 2024). "The gastric cancer cell lines MKN-45 and SGC-7901 were cultured in CM from GCAFs for 72 h, and flow cytometry was performed to evaluate the percentage of CSC-like cells based on the expression of the cell surface markers CD44 and CD24." (PMID 31139014, 2019). "The results obtained in this study clearly established a novel relationship between CD24 and EGF/EGFR signaling in the context of migration regulation, which could be essential in promoting aggressiveness of gastric cancer." (PMID 26830684, 2016). "Here, we investigated the relationship between CD24 and EGFR in gastric cancer cells." (PMID 26830684, 2016). "Changes of cells morphology and reduced CD24 and MYLK expression further supported the conclusion that depression of cell mobility could be the major consequence of MTA2 knockdown in gastric cancer cells." (PMID 25929737, 2015). "PBMCs from gastric cancer patients were stained with various combinations of monoclonal antibodies to proteins which have been suggested for use in identifying Bregs, including: CD5, CD1d, CD38, CD24, IgM, CD25, CD10, and CD21." (PMID 26378021, 2015). "Based on these previous studies, we hypothesized that CD24 and CD44 expression might be correlated with gastric cancer prognosis." (PMID 25212506, 2014). "CD24 and CD44 expression were detected in the membrane of cancer cells in gastric cancer samples." (PMID 25212506, 2014). "Weak staining for both CD24 and CD44 was also observed in the nucleus of gastric cancer cells." (PMID 25212506, 2014). "Cancer stem cells (CSCs) have recently been identified in human gastric cancer cell lines in several studies, and CD44(+)CD24(+) cells have been shown to define a highly tumorigenic, gastric cancer cell population with properties of self-regeneration and multi-lineage differentiation." (PMID 25212506, 2014). "Multivariate regression analysis indicated that positive CD44 expression (P = 0.029), TNM staging (P < 0.001), and lymphovascular invasion (P = 0.016), but not CD24 expression (P = 0.065), were independent prognostic factors in gastric cancer." (PMID 25212506, 2014).
gastric cancer (continued). "The present study simultaneously analyzed CD24 and CD44 expression levels independently and showed that positive expression of CD44 alone, but not CD24, was associated with poor survival in gastric carcinoma." (PMID 25212506, 2014). "Compared to patients who were CD24-, those with CD24+ had higher likelihood to have gastric cancer recurrence but without significance (OR = 1.86, 95% CI: 0.52-6.61, P = 0.339)." (PMID 22839505, 2012). "CD24+ patients showed no greater significance of gastric cancer recurrence than CD24- patients (OR = 1.86, 95% CI: 0.52-6.61, P = 0.339)." (PMID 22839505, 2012). "Although CD24+ patients had a higher likelihood of gastric cancer recurrence than CD24- patients, significance was not demonstrated." (PMID 22839505, 2012). "Since adhesion molecules CD44 and CD24 do not appear to be clinically useful for prediction of gastric carcinoma recurrence after curative resection, future research is warranted to both confirm these results and to investigate other possible biomarkers." (PMID 22839505, 2012). "In conclusion, neither individual expression of CD24 and CD44 nor combined expression of CD44/CD24 was associated with recurrence of gastric carcinoma." (PMID 22839505, 2012). "Although CD44+CD24+ and CD44+CD54+ cells have clinical relevance in patients with GC, it is still necessary to determine whether these cells with self-renewal capability are true gastric cancer stem cells (GCSCs)." (PMID 36737794, 2023). "However, after adjusting for other risk factors, the association of CD44 expression (aOR = 0.66, 95% CI: 0.10-4.26, P = 0.658) and CD24 expression (aOR = 0.09, 95% CI: 0.01-1.35, P = 0.081) with gastric cancer recurrence were still not significant." (PMID 22839505, 2012). "In this study, we aimed to analyze the effects of mtDNA content on cell surfacepositivity for anti-CD24 and anti-CD44 antibodies and chemoresistance level in AGS, HGC-27 and MKN-45 gastric cancer(GC) cell lines and to determine a setpoint for mtDNA copy for each cell line." (PMID 29845783, 2018). "It was also reported that expression level of Hedgehog-related proteins was higher in gastric cancer stem cells expressing both CD44 and CD24 compared with non-expressing ones." (PMID 29642386, 2018). "The contents of CD24 and epidermal growth factor receptor (EGFR) in gastric cancer cells (SGC-7901 and BGC-823) and non-malignant gastric epithelial cells (GES-1) were evaluated by Western blotting assay." (PMID 26830684, 2016). "Previously, gastric TICs have been identified by using CD44, CD44 and EpCAM, CD44 and CD24, CD44 and CD54, CD90, and aldehyde dehydrogenase 1 as markers, but CD49f has not been used to detect TICs in gastric cancers." (PMID 24015244, 2013). "After adjusting for other risk factors, the association of CD44 expression (aOR = 0.66, 95% CI: 0.10-4.26, P = 0.658), CD24 expression (aOR = 0.09, 95% CI: 0.01-1.35, P = 0.081) or combined (CD44/CD24) with gastric cancer recurrence were not significant." (PMID 22839505, 2012).
autoimmune disease (34 papers, 2008 to 2026). A disorder resulting from loss of function or tissue destruction of an organ or multiple organs, arising from humoral or cellular immune responses of the individual to their own tissue constituents. "CD24, which carries polymorphisms linked to the progression of autoimmune disorders, and JCHAIN genes were differentially expressed in both AL and CA lesions compared to NAWM for three donors." (PMID 39596026, 2024). "Previous studies have demonstrated that CD24 polymorphisms are associated with an increased risk of autoimmune diseases, including systemic lupus erythematosus, multiple sclerosis, and rheumatoid arthritis." (PMID 39221249, 2024). "CD24 polymorphisms are linked to the progression of autoimmune disorders, including systemic lupus erythematosus (SLE), multiple sclerosis and rheumatoid arthritis." (PMID 38313430, 2023). "CD24 is involved in the regulation of the immune response and has been implicated in the pathogenesis of autoimmune diseases." (PMID 38313430, 2023). "For example, genetic alteration of CD24, such as deletion or polymorphisms of the CD24 gene, is associated with increased risk for autoimmune disease, including systemic lupus erythematosus and multiple sclerosis." (PMID 35289116, 2022). "CD24 gene polymorphisms have also been implicated in the pathogenesis and progression of several autoimmune diseases." (PMID 36294907, 2022). "Our findings are consistent with previous studies showing that elevated CD24 levels are associated with inflammation and autoimmune diseases such as inflammatory bowel disease, rheumatoid arthritis, and multiple sclerosis." (PMID 34575716, 2021). "Many experimental studies have focused on investigating the associations of CD24 polymorphisms with autoimmune diseases such as MS, systemic lupus erythematosus (SLE), rheumatoid arthritis or giant cell arthritis (and references therein)." (PMID 26039238, 2015). "The findings of our study are in accordance with previous case-control studies showing that the 226 C>T polymorphism of CD24 is associated with another autoimmune disease, the SLE." (PMID 26039238, 2015). "Clinical data provide substantial support for the association between CD24 and autoimmune diseases." (PMID 38313430, 2023). "For example, the rs8734 polymorphism in CD24 was associated with susceptibility to diverse autoimmune diseases including rheumatoid arthritis (RA), autoimmune thyroid disease (AITD), systemic lupus erythematosus (SLE), multiple sclerosis (MS), and inflammatory bowel disease (IBD)." (PMID 28702029, 2017). "Importantly, clinical studies have reported that the polymorphisms of human CD24 are associated with risk and progression of several autoimmune diseases, multiple sclerosis and rheumatoid arthritis (RA)." (PMID 27955675, 2016). "Importantly, polymorphisms of human CD24 are associated with risk and progression of several autoimmune diseases, multiple sclerosis and RA." (PMID 27955675, 2016). "CD24 is a small heavy glycosylated protein, which plays a critical role in neural development and acts as an inflammatory suppressor in tumors and autoimmune diseases." (PMID 39953809, 2025). "More importantly, growing research has uncovered vital functions of CD24 in a range of pathological states, such as autoimmune disorders, sepsis metabolic disorders, graft vs host diseases." (PMID 38313430, 2023). "This review encapsulates the expanding spectrum of CD24 functions, delving into its involvement in immune regulation, cancer immune microenvironment, and its potential as a therapeutic target in autoimmune diseases and beyond." (PMID 38313430, 2023). "The precise mechanism through which CD24 influences autoimmune diseases remains to be fully understood." (PMID 38313430, 2023). "Low levels of circulating CD24+CD38+cells were seen in patients with active autoimmune diseases such as active RA." (PMID 36661897, 2022).